FGF19 (fibroblast growth factor 19)
Diseases named in the same sentence as FGF19 in open-access papers (continued):
Sharing a sentence is not in itself a finding about the gene and the disease.
liver disease (13 papers, 2015 to 2025). "This inflammation was linked to liver disease, with notable dysregulation in biomarkers matrix metalloproteinase-2, matrix metalloproteinase-9, and fibroblast growth factor-19." (PMID 39471521, 2025). "Experimental studies linked dysfunctional Farnesoid X receptor (FXR)-fibroblast growth factor 19 (FGF19) signaling to liver disease." (PMID 38332428, 2024). "FGF19 also correlates with severity of liver disease measured both by laboratory parameters and Mayo Risk score and is associated with impaired HRQoL." (PMID 26293907, 2015). "Differences in correlations with basic biochemical parameters depending on the primary liver disease suggest unique functions of FGF19 and FGF21 in various clinical contexts." (PMID 39941067, 2025). "These scientists believe that the reason for such high concentrations of FGF19 is the presence of factors accompanying primary liver diseases, such as increased stress or chronic inflammation, eliminated after transplantation." (PMID 39941067, 2025). "In fact, FGF19 analogs are now considered promising medication for hepatic disorders, such as NASH and NAFLD, whereby NGM282 is currently part of clinical trials." (PMID 35682726, 2022). "FGF19 correlates with severity of liver disease and can potentially serve as an indicator of chronic cholestatic liver injury." (PMID 26293907, 2015). "Using a comprehensive panel of circulating organokines, including fibroblast growth factor (FGF) 19, FGF21, adiponectin, galectin-3, irisin, and leptin, along with choline metabolites, we characterized metabolic signaling patterns associated with liver disease severity." (PMID 40943431, 2025). "Similar to the observations from HCC cells, overexpression of FGF19 suppressed E-cadherin expression and promoted EMT in HL7702 normal liver cells, implicating that FGF19-induced EMT may also play a critical role in cirrhotic liver diseases." (PMID 26498355, 2016). "MMP-2, MMP-9, and FGF-19 levels were dysregulated among the HIV/HBV–co-infected, and 11% of HIV/HBV–co-infected had evidence of undiagnosed advanced liver disease." (PMID 39471521, 2025). "The FGF19 analogs lacking its mitogenic activity are also considered as a promising candidate for hepatic disorders, such as NASH and NAFLD." (PMID 35682726, 2022). "Conversely, regarding FGF19 activity and its analogs in the liver, we do not have enough data to understand how these compounds suppress Cyp7a1 and genes that facilitate hepatic disorder development." (PMID 35682726, 2022). "Previous studies suggest that circulating FGF19 are increased in patients with various liver diseases, involving alcoholic hepatitis as well as PBC; however, the general function of serum FGF19 and synthesis of BA in PBC-AIH OS is still unclear and warrants further investigation." (PMID 32626734, 2020). "As previously seen with both FGF19 and FGFR4, EpCAM expression also appeared to increase with the histological severity of inflammation and liver disease, demonstrating a significant positive correlation between EpCAM expression and histopathologic changes from ST to HCC (r = 0.947)." (PMID 27447573, 2016). "Studies have shown that FGF19 and CRP levels can be positively correlated in most liver diseases, but a negative correlation may occur in other conditions, such as viral infections." (PMID 39941067, 2025).
Cholestatic liver disease (12 papers, 2012 to 2023). "As expected, serum FGF19 correlates with severity of cholestatic liver disease where increases in serum FGF19 is associated with a decrease in CYP7A1 expression." (PMID 33414764, 2020). "Recently, FGF19 has been identified as a promising therapeutic target for diabetes, cholestatic liver disease, non-alcoholic steatohepatitis (NASH), and abnormalities of BA metabolism as a result of its remarkable pharmacological capabilities." (PMID 37789318, 2023). "Farnesoid X receptor (FXR) agonists and fibroblast growth factor 19 (FGF19) analogues suppress bile acid synthesis and are being investigated for their potential therapeutic efficacy in cholestatic liver diseases." (PMID 36176935, 2022). "Furthermore, FXR agonists as well as a fibroblast growth factor 19 (FGF19) analogue are currently tested in clinical trials for different cholestatic liver diseases." (PMID 34566994, 2021). "In addition, besides alterations in the enterohepatic bile acid circulation, factors that affect the levels of circulating C4 and FGF19 include the diurnal variation in hepatic bile acid synthesis, cholecystectomy, and extrahepatic and intrahepatic cholestatic liver disease." (PMID 36148443, 2022). "However, nontumorigenic FGF19 variants have been engineered and used to treat cholestatic liver disease and regulate glucose homeostasis." (PMID 33783283, 2021). "This overview focuses on the central roles of farnesoid X receptor, fibroblast growth factor 19, and apical sodium-dependent bile acid transporter for the enterohepatic circulation of bile acids and their potential as new drug targets for the treatment of cholestatic liver disease." (PMID 27134744, 2016). "FXR activation promotes the release of ileal FGF19 (the human homolog of murine FGF15) which suppresses bile acid synthesis by repressing CYP7A1 expression and therefore FGF19 analogs may be a potential therapeutic target for pediatric cholestatic liver diseases." (PMID 32432119, 2020).
lung carcinoma (11 papers, 2014 to 2023). "As a prominent oncogene, FGF19 has been implicated in the progression of numerous carcinomas, like thyroid cancer, gastric cancer and lung cancer 20-22." (PMID 36923538, 2023). "A higher serum level of FGF19 was found in lung cancer patients, which could also serve as a novel diagnostic index to screen lung cancer." (PMID 32111983, 2020). "Knockdown of CCND1 was found to prolong survival by attenuating FGF19-induced cell proliferation in a murine lung cancer model." (PMID 35463335, 2022). "For instance, like methylation of the KL promoter region, how epigenetic regulation of KLB expression in relation to FGF19/FGFR4 signaling during lung cancer progression remains an interesting question." (PMID 31695781, 2019). "Four of these markers (BRAF, EGFR, LZTS1, and FGF19) have been directly correlated with lung cancer development and progression." (PMID 25397880, 2014). "In disease states, FGF19 is crucial for the development and progression of several cancers such as head and neck squamous cell carcinoma, hepatocellular carcinoma, and lung cancer." (PMID 35463335, 2022). "To verify whether serum levels of FGF19 in lung cancer patients corresponded with the observations of high CNV and mRNA expression from the database, we further analyzed clinical samples." (PMID 32111983, 2020). "The non-invasive and affordable diagnosis of lung cancer can beaided by salivary mRNA biomarkers (CCNI, EGFR, FGF19, FRS2, and GREB1)." (PMID 37693919, 2022). "The logistic regression model combining the five mRNA biomarkers (CCNI, EGFR, FGF19, FRS2, and GREB1) can distinguish patients with lung cancer from normal controls (area under the receiver operating characteristic curve [AUC-ROC] = 0.925; sensitivity = 93.75%; specificity = 82.81%)." (PMID 35651679, 2022). "Fibroblast growth factor (FGF) isoforms, such as FGF4, FGF19 and FGF7, promoted epithelial-mesenchymal transition (EMT), cell proliferation and migration during cancer progression by inducing store-operated calcium entry in lung carcinoma." (PMID 33005178, 2020). "It appeared that the FGF19/FGFR4 signaling could still function in lung cancer independent of KLB." (PMID 31695781, 2019).
non-alcoholic steatohepatitis (11 papers, 2013 to 2025). "There is another study also demonstrating profound antisteatotic, anti-inflammatory, and antifibrotic activities of a therapy based on the administration of engineered FGF19 variant in diet-induced mouse models of non-alcoholic steatohepatitis (NASH)." (PMID 31847428, 2019). "This variant FGF19 is in clinical development for the treatment of patients with non-alcoholic steatohepatitis." (PMID 30322054, 2018). "We investigated the association of serum FGF21, FGF19 and liver Klotho coreceptor with non-alcoholic steatohepatitis (NASH) and fibrosis in children with NAFLD." (PMID 23840612, 2013). "Recently, FGF19 analogues or mimics are entering phase 3 clinical research in nonalcoholic steatohepatitis (NASH)." (PMID 35847588, 2022). "FXR agonist obeticholic acid and engineered FGF19 analog NGM282 have been shown to improve non-alcoholic steatohepatitis (NASH) in clinical trials." (PMID 32681035, 2020). "NGM282, an engineered FGF19 analog, is currently in clinical development for treating nonalcoholic steatohepatitis." (PMID 30679232, 2019). "FGF19 is considered anticholestatic and hepatoprotective in rodents, and recent clinical studies have shown promising beneficial effects in both patients with nonalcoholic steatohepatitis and primary sclerosing cholangitis treated with an engineered FGF19 analog." (PMID 38836805, 2024). "Given the findings of these studies, there are emerging medical therapies for treatment of nonalcoholic steatohepatitis (NASH) that include agonists of FXR and FGF19 analogs." (PMID 35116006, 2021).
extrahepatic cholestasis (10 papers, 2015 to 2024). Impairment of the bile flow caused by an obstruction in the portion of the bile duct system located outside of the liver. "For aldafermin-treated mice, plasma FGF19 concentrations of ∼600 pg/ml were measured, whereas persons with extrahepatic cholestasis reach levels higher than 2 ng/ml." (PMID 38074508, 2024). "This is supported by the finding that plasma and hepatic FGF19 levels were elevated in extrahepatic cholestasis." (PMID 25798860, 2015). "Elevated plasma levels of FGF-19 have been found in patients with extrahepatic cholestasis, suggesting that FGF-19 regulation may provide promising therapeutic potential in such metabolic diseases." (PMID 36864554, 2023).
Hyperglycemia (10 papers, 2011 to 2026). An increased concentration of glucose in the blood. "Our data showed that FGF19 administration alleviated the hyperglycaemia and impaired glucose tolerance in obese mice." (PMID 33751819, 2021). "Here, serum FGF19 levels were reduced in HIV-infected patients with metabolic disturbances including hyperglycemia and insulin resistance, whereas FGF21 levels were increased." (PMID 24260557, 2013). "Recordings were performed in control and T1DM mice to understand whether hyperglycemia modulates the effect of FGF19 in these neurons as suggested by previous findings." (PMID 34858337, 2021). "It would be of interest to conduct studies on a cellular level investigating whether postprandially upregulated bile acids and FGF-19 differentially regulate the activation of beta Klotho in a given metabolic context such as hyperlipidemia or hyperglycemia." (PMID 26863103, 2016). "Exogenous administration of FGF19 and its analog NGM282 did not correct hyperglycemia in diabetic patients, but caused a rapid and sustained reduction in hepatic Cyp7a1 levels and liver fat content in NAFLD patients." (PMID 34362888, 2021). "The mechanism by which FGF21 and FGF19 ameliorate hyperglycemia in diabetic animals is not well understood." (PMID 21437243, 2011).
prostate carcinoma (10 papers, 2010 to 2025). A carcinoma that arises from epithelial cells of the prostate gland. "Among endocrine FGFs, the association between FGF19 and malignant diseases such as liver cancer, colon cancer, and prostate cancer was demonstrated." (PMID 30720727, 2019). "Silencing FGF19 in prostate cancer cells expressing autocrine FGF19 reduced their invasion and proliferation in vitro and tumor growth in vivo." (PMID 40004457, 2025). "FGF19 induces the expression of markers of epithelial mesenchymal transition in hormone-sensitive prostate cancer cells." (PMID 30720727, 2019). "In prostate cancer cells, FGF19 stimulates cell proliferation and cell invasion through activation of MAP kinase and AKT pathways." (PMID 30720727, 2019). "In prostate cancer, FGF19/FGFR signaling promotes cancer progression along with the presence of KLa and/or KLb as co-factors." (PMID 29731962, 2018). "Given that classical FGFs and FGF19 are also increased in prostate cancer, we analyzed expression microarrays hybridized with RNAs from of LNCaP cells stimulated with FGF2, FGF19 or FGF23." (PMID 26019137, 2015). "Serum FGF19 levels in the high Gleason grade of prostate cancer are higher than those in the low Gleason grade group, indicating that FGF19 promotes the progression of prostate cancer." (PMID 26483756, 2015). "Using DU145 prostate cancer cells, we demonstrate that FGF19 stimulation results in a decrease in TNFα-induced apoptosis." (PMID 21203561, 2010). "FGF19 stimulation of endogenous FGFR4 in TNFα-treated DU145 prostate cancer cells also leads to a decrease in IKKβ activity, concomitant reduction in NFκB nuclear localization, and reduced apoptosis." (PMID 21203561, 2010). "Next we examined the effect of FGF19 treatment on TNFα-induced apoptosis in the DU145 prostate cancer cell line." (PMID 21203561, 2010). "FGF1, FGF2, FGF6, FGF8, FGF19 and FGF23 are involved in prostate cancer development and progression." (PMID 33655556, 2021).
head and neck squamous cell carcinoma (9 papers, 2017 to 2026). A squamous cell carcinoma that arises from any of the following anatomic sites: lip and oral cavity, nasal cavity, paranasal sinuses, pharynx, larynx, and salivary glands. "In head and neck squamous cell carcinoma (HNSCC), amplification of 11q13, containing among others CCDN1, FGF3, and FGF19, is frequent and has been linked with a poor prognosis." (PMID 39324009, 2024). "Furthermore, FGF19 is critical for the progression of breast cancer, prostate cancer, head and neck squamous cell carcinoma and thyroid cancer." (PMID 32111983, 2020). "In a previous study on head and neck squamous cell carcinoma(HNSCC), FGF19 was overexpressed in tumours and promoted cell proliferation." (PMID 37782406, 2024). "CCND1 is also frequently co-amplified with FGF19 in head and neck squamous cell carcinoma, amplification of which was seen in 18 (35%) of patients in our cohort—FGF19 is involved in HNSCC tumorigenesis and may be useful as a target for therapy." (PMID 39324009, 2024). "Of note, while aberrant FGF19 expression is frequent in HCC, other types of tumors, such as head and neck squamous cell carcinoma, have been shown to be driven by FGF19, our findings might therefore also be of interest in these contexts." (PMID 38228803, 2024).
sarcopenia (9 papers, 2021 to 2025). Progressive decline in muscle mass due to aging which results in decreased functional capacity of muscles. "Functional studies in animal models have validated this axis, and preliminary human data reveal significant associations among fecal microbiota composition, plasma FGF19 levels, and muscle mass in older adults and individuals with sarcopenia." (PMID 41568005, 2025). "Fibroblast growth factor 19 (FGF19) has significant regenerative, metabolic, and anti-inflammatory properties associated with skeletal muscle growth and hypertrophy, while low levels of FGF19 are associated with sarcopenia." (PMID 38201893, 2023). "The pathogenesis of sarcopenia is related to skeletal muscle metabolism, and FGF19 has been found to play a role in muscle metabolism." (PMID 40969368, 2025). "Lower BMI, lower serum ALB, FGF19, TNF-α, and higher circulating GDF11 are associated with sarcopenia." (PMID 40969368, 2025). "Compared with circulating factors in non-sarcopenia older adults, FGF19 and GDF11 were significantly higher in sarcopenia older adults." (PMID 40969368, 2025). "In OP and sarcopenia, endocrine-derived FGFs (FGF19, FGF21, and FGF23) modulate bone mineral synthesis and decomposition as well as muscle tissues." (PMID 38902808, 2024). "Here, we tested the effects of a treatment with recombinant human FGF19 in a CKD mouse model, which associates sarcopenia and metabolic disorders." (PMID 37015932, 2023). "In a study of older adults (most of whom had sarcopenia or probable sarcopenia), FGF 19 levels were negatively correlated with muscle fiber length." (PMID 37614743, 2023). "It has also been reported that exogenous FGF19 induces skeletal muscle hypertrophy and blocks muscle atrophy induced by glucocorticoid treatment, sarcopenia and obesity." (PMID 34362888, 2021). "We also found that FGF19 was lower in the sarcopenia group than in the non-sarcopenia group." (PMID 40969368, 2025). "The negative association between FGF19 and sarcopenia was also confirmed by a recent cross-sectional study in Turkey of 88 older adults outpatient participants aged 65 years or older." (PMID 40969368, 2025). "Additionally, some studies suggest that FGF19, as a potential target for treating metabolic diseases, may be a promising new factor in the treatment of sarcopenia." (PMID 40969368, 2025). "Therefore, FGF19 may be an emerging factor for the treatment of sarcopenia, and can contribute to the diagnosis and prevention of sarcopenia." (PMID 40969368, 2025). "Therefore, our results suggest that FGF19 may represent a novel interesting therapeutic strategy for a global improvement of sarcopenia and metabolic complications in CKD." (PMID 37015932, 2023). "BMI, serum ALB, FGF19, and TNF-α levels were lower in the older adults population with sarcopenia, while GDF11 was higher in the serum of patients with sarcopenia." (PMID 40969368, 2025). "Animal studies showed that the exogenous FGF 19 administration improved muscle mass and grip strength, and increased the transverse diameter of their myotubes; serum FGF 21 levels are positively correlated with aging-induced sarcopenia." (PMID 37614743, 2023). "A cross-sectional study demonstrated a significant decrease in serum FGF19 levels and a significant increase in serum FGF21 levels among elderly individuals with sarcopenia compared to those without sarcopenia." (PMID 38902808, 2024).
gestational diabetes (8 papers, 2016 to 2025). Carbohydrate intolerance first diagnosed during pregnancy. "Since reduced FGF19 level is a contributing factor in the development of gestational diabetes, it created much interest in understanding the role of FGF21." (PMID 30927227, 2019). "Although studies suggest that reduced FGF19 level may play a role in the pathophysiology of gestational diabetes, the increased FGF21 level may be a response to the disease." (PMID 30927227, 2019). "Gestational diabetes mellitus (GDM) (de novo glucose intolerance in pregnancy) is a common cause of enhanced fetal insulin secretion and overgrowth, and has been associated with reduced maternal circulating FGF19 levels and placental FGF19 expression, and reduced fetal insulin sensitivity." (PMID 35145481, 2021).